UGT2B11 (UDP glucuronosyltransferase family 2 member B11)
Description:
UDP-glucuronosyltransferase (UGT) that catalyzes phase II biotransformation reactions in which lipophilic substrates are conjugated with glucuronic acid to increase the metabolite's water solubility, thereby facilitating excretion into either the urine or bile. Exhibits narrow substrate specificity and very low catalytic activity compared to other UGT2B subfamily members. Preferentially glucuronidates catechol estrogens. Also conjugates estriol and 3alpha-hydroxysteroids with activities 30-90 fold lower than UGT2B7. Shows no activity toward testosterone, hyodeoxycholic acid or most drugs. Physiological role remains unclear due to limited substrate range and low catalytic efficiency.
Tractability: Antibody: UniProt predicts a signal peptide or a membrane-spanning region.
Gene: Protein-coding gene on chromosome 4 (69,199,951 to 69,214,748, reverse strand). Ensembl gene ENSG00000213759.
Subcellular location: Microsome membrane; Endoplasmic reticulum membrane
Pathways (Reactome):
Drug ADME: Aspirin ADME
Metabolism: Glucuronidation
Gene Ontology:
Molecular function: glucuronosyltransferase activity; protein binding; UDP-glycosyltransferase activity
Biological process: androgen metabolic process; estrogen metabolic process; xenobiotic metabolic process
Cellular component: endoplasmic reticulum membrane
Genetic constraint (gnomAD): Loss-of-function variants: 41 observed, 43.63 expected, observed/expected ratio (o/e) 0.94, 90% interval 0.73 to 1.22. The synonymous counts are far from expectation, so gnomAD's model fits this gene poorly and the ratio says little. Missense variants: 765 observed, 570.88 expected, observed/expected ratio (o/e) 1.34, 90% interval 1.26 to 1.42. Synonymous variants: 260 observed, 197.8 expected, observed/expected ratio (o/e) 1.31, 90% interval 1.19 to 1.46.
Homologues: Orthologues: zebrafish ugt2a7 (51% identical), zebrafish ugt2b5 (49% identical), zebrafish ugt2b1 (49% identical), zebrafish ugt5a1 (41% identical), zebrafish si:ch73-334d15.1 (41% identical), zebrafish ugt5a2 (41% identical), zebrafish ugt5c1 (39% identical), zebrafish ugt5g1 (39% identical), zebrafish ugt5b4 (39% identical), zebrafish ugt5c3 (39% identical), zebrafish ugt5b2 (38% identical), zebrafish ugt5c2 (38% identical), and 93 more. Paralogues in human: UGT2B28 (95% identical), UGT2B10 (91% identical), UGT2B4 (86% identical), UGT2B7 (86% identical), UGT2B15 (77% identical), UGT2B17 (77% identical), UGT2A2 (59% identical), UGT2A3 (59% identical), UGT2A1 (51% identical), UGT1A10 (43% identical), UGT1A3 (43% identical), UGT1A7 (43% identical), and 9 more.
Diseases named in the same sentence as UGT2B11 in open-access papers:
UGT2B11 is named in the same sentence as 8 diseases in open-access papers, as found by Europe PMC text mining. Sharing a sentence is not in itself a finding about the gene and the disease. The quoted sentences say what the papers report.
breast carcinoma (3 papers, 2010 to 2023). "We also observed suggestive association for UGT2B11 in breast and endometrial cancer as well as for HSD11B1, SULT2A1 and SULT2B1 in breast cancer." (PMID 20617168, 2010).
prostate carcinoma (3 papers, 2021 to 2022). A carcinoma that arises from epithelial cells of the prostate gland. "Elevated UGT2B11 expression during the treatment of prostate cancer with cisplatin-based drugs may indicate that the body has developed resistance to these drugs and that androgen deprivation therapy or immunotherapy may be used to treat the prostate cancer." (PMID 36741721, 2022). "The UGT2B11 mRNA affects the IC50, EC50, and AUC of anti-prostate cancer drugs and confers resistance to cisplatin-based drugs." (PMID 36741721, 2022).
prostate tumours (1 paper, 2020). "Similar to normal prostate tissue, prostate tumours expressed several UGT2B mRNAs, including UGT2B17 but also UGT2B4, UGT2B7, UGT2B10, UGT2B11, UGT2B15 and UGT2B28." (PMID 32047296, 2020).
renal disease (1 paper, 2019). "The GWAS also implicated a locus encoding a UGT, UGT2B11, in the renal disease susceptibility." (PMID 31040861, 2019). "Therefore, we hypothesize that the renal disease associated UGT2B11 variant identified in the Tiwi may compromise an ability to conjugate and thus excrete a nephrotoxic xenobiotic or produce a nephrotoxic xenobiotic by conjugation of pro-substance." (PMID 31040861, 2019). "Two of these loci, single nucleotide polymorphisms (SNPs) rs443816 located in the gene encoding UGT2B11 and rs4016189 located in the gene encoding CRIM1, were also significantly associated with the renal disease phenotype in an independently sampled cohort." (PMID 31040861, 2019).
tumor (1 paper, 2023). "IL1RL1, PCDHGA3, STMN2, and UGT2B11 showed no expression with tumor microenvironment components." (PMID 37985782, 2023).
UGT2B11 also shares sentences with these, for which no sentence is quoted: cancer (2 papers); endometrial cancer (1); hepatocellular carcinoma (1).